SST (somatostatin)
Diseases named in the same sentence as SST in open-access papers (continued):
Sharing a sentence is not in itself a finding about the gene and the disease.
schizophrenia (continued). "Other neuropsychiatric disorders, such as schizophrenia and bipolar disorder, showed a reduction in SST gene expression and fewer SST-expressing neurons in various brain areas." (PMID 35052772, 2022). "In individuals with schizophrenia, PV and SST gene expression is reduced across multiple areas of the cortical working memory network." (PMID 34536352, 2021). "It should be noted that although research regarding schizophrenia focus on PV interneurons as a reason for pathophysiology, the functions of SST interneurons are also widely affected in the prefrontal cortex in the patients." (PMID 34055795, 2021). "In schizophrenia, gene and protein expression of interneuron markers, particularly parvalbumin (PV) and somatostatin (SST), are often reduced in the cortex, cerebellum, and hippocampus." (PMID 34174930, 2021). "Multiple studies have found reduced SST mRNA in postmortem brain tissue from patients with schizophrenia, specifically in working memory networks, implicating their potential dysfunction in the disease." (PMID 34731619, 2021). "It is intriguing that targeting mPFC SST-INs reverses schizophrenia-like deficits in light of abundant evidence of PV-IN dysfunction in schizophrenia." (PMID 34731619, 2021). "Acute administration of an N-methyl-d-aspartate (NMDA) receptor antagonist used to model cortical inhibitory deficits also suppresses mPFC SST-IN activity and produces schizophrenia-like behavioral deficits." (PMID 34731619, 2021). "Attenuated sleep oscillations, altered sleep patterns, and dysfunctional PV+ and SST+ GABAergic interneurons have also been observed in schizophrenia, which is a multifaceted mental disorder characterized by cognitive deficits." (PMID 34588960, 2021). "A recent study has demonstrated a reduced SST interneurons’ density in schizophrenia patients and profound laminar deficit with an increase of death receptor (apoptotic activity)." (PMID 34055795, 2021). "In patients with schizophrenia and bipolar disorder, somatostatin positive neurons decreased in the amygdala." (PMID 32802040, 2020). "This comprehensive profiling of SST and PVALB interneuron expression is necessary for deep profiling of their relationship to in-vivo brain function and subsequent schizophrenia risk through statistical genetic approaches." (PMID 32514083, 2020). "DNA microarray for expression of GABA-related transcripts in the dorsolateral PFC of schizophrenic subjects (post mortem tissue) and matched controls revealed a robust decrease in SST mRNA in subjects with schizophrenia." (PMID 33192369, 2020). "We have previously examined the role of SST and PV interneurons in the regulation of cognitive function by transplanting stem-cell derived PV and SST neuron transplants in the vHipp of a rodent model of schizophrenia." (PMID 31636253, 2019). "Once again, the level of cortical SST mRNA negatively correlated with the density of SST+ IWMNs in schizophrenia cases." (PMID 31285426, 2019). "The LIMMA analysis first detected a number of down-regulated genes in individuals with EDs that are known to be suppressed in schizophrenia or major depressive disorder, such as SST, NPY, SLC32A1, HINT1, and RELN." (PMID 29958387, 2018). "Disturbances in the parvoalbumin and somatostatin activity have been commonly reported in the prefrontal cortex from subjects with schizophrenia." (PMID 28626390, 2017). "For example, modulators of NPY or SST signaling and drugs that increase the activity of the GABAergic pathway have been reviewed as attractive therapeutic opportunities for schizophrenia." (PMID 28809853, 2017). "SST has also been implicated in several neurological diseases, and reduced level of SST in the brain and the cerebrospinal fluid has been observed in patients with Alzheimer disease, Parkinson disease, Schizophrenia, and Huntington disease." (PMID 32309597, 2017).
schizophrenia (continued). "Patients with Schizophrenia have been reported to have a decrease in SST neurons and mRNA as well as an increase in rhythmic theta activity." (PMID 25359633, 2014). "The expression levels of parvalbumin and somatostatin have previously been reported to be reduced in patients with schizophrenia in the TRC collection." (PMID 22545112, 2012). "For example, the mRNAs encoding parvalbumin (PV) and somatostatin (SST), each of which is expressed in a separate subset of cortical GABA neurons, are decreased in schizophrenia." (PMID 22937123, 2012). "This change parallels our previous finding of reduced interneuron marker mRNA (somatostatin) being correlated with increased IWMN density in schizophrenia, and is consistent with a failure of migration of some newly born neurons to the cortex in development." (PMID 21966452, 2011). "It regulates BDNF, altering the expression of downstream GABAergic transcripts (NPY, SST and PV) in schizophrenia patients." (PMID 20156358, 2010). "Previous studies have indicated that chronic stress, a significant factor in the onset of depression, can increase synaptic inhibition mediated by PV-Ins and reduce the expression of parvalbumin and somatostatin in postmortem tissue from schizophrenia patients." (PMID 40931040, 2026). "Collectively, these results highlight the therapeutic potential of 5-HT4R activation in pyramidal, parvalbumin+, and somatostatin+ neurons of hippocampal–prefrontal pathways for mitigation of cognitive and negative symptoms associated with schizophrenia." (PMID 40332153, 2025). "Thus, modulating VIP+ and/or SST+ interneuron activity holds therapeutic potential for addressing GABAergic hypofunction in schizophrenia." (PMID 39916937, 2024). "Moreover, the distribution of IDAC alterations in patients with schizophrenia is consistent with the cortical distribution of parvalbumin and somatostatin GABA interneurons, further supporting the evidence of a deficient GABA system in this disorder." (PMID 39122060, 2024). "Besides GAD1 expression, there is additional convincing evidence for the alterations of SST mRNA expression in schizophrenia." (PMID 37131313, 2023). "Therefore, the areas most affected in patients with schizophrenia characteristically show a high density of parvalbumin or somatostatin GABA interneurons, which interestingly both developmentally derive from the medial ganglionic eminence of the subpallium." (PMID 37848404, 2023). "A stereological study with immunohistochemical staining of interneurons in schizophrenia found lower numbers of somatostatin-expressing interneurons in CA4, CA2/3, and CA1 and of parvalbumin-immunoreactive interneurons in CA4 and CA1 but no changes in total neuron number." (PMID 36291109, 2022). "Interestingly, cellular, molecular and synaptic changes to SST+ interneurons have also been found in patients with schizophrenia." (PMID 35854005, 2022). "While fast-spiking PV interneurons (PV-INs) have historically garnered the most attention in schizophrenia research, recent findings suggest a significant role of the lesser studied SST interneurons (SST-INs) in mPFC function, working memory, and the pathophysiology of schizophrenia." (PMID 34731619, 2021). "Furthermore, increased gene expression of the viral restriction factor interferon-induced transmembrane protein (IFITM) is linked to lower expression of GABA-related mRNAs, including GAD1 and SST, in the cortex of schizophrenia cases." (PMID 34174930, 2021). "It is unknown whether there are molecular changes in GAD1, PV and SST transcripts in the midbrain in schizophrenia." (PMID 34174930, 2021). "Changes in the Pvalb and SSt transcripts seen in adult mGlu5−/− mice are consistent with the view that these mice recapitulate some of the biochemical and behavioral hallmarks of schizophrenia." (PMID 33962661, 2021). "Postmortem evidence suggests a region-specific effect of SST neurons in schizophrenia." (PMID 34746116, 2021).
schizophrenia (continued). "The possible greater pathology in SST mRNA-containing neurons as compared with PV-containing neurons in people with schizophrenia may be a key finding for consideration when developing relevant animal models for schizophrenia." (PMID 34055795, 2021). "However, in a rat model of schizophrenia, maternal immune activation paradigm, increased white matter somatostatin-positive inhibitory neurons have been noticed." (PMID 33384588, 2020). "The levels of SST mRNA were not altered in the dorsolateral PFC of monkeys chronically exposed to antipsychotic medications, suggesting that administration of antipsychotics as a treatment itself is not the cause of the reduced SST mRNA in schizophrenia." (PMID 33192369, 2020). "Moreover, subjects with schizophrenia show greater post-mortem reductions in somatostatin interneurons than other kinds (at least in the dorsolateral prefrontal cortex), and a deficit in GABA release in mTL (especially if antipsychotic-naïve)." (PMID 32236540, 2020). "Links between specific risk factors, such as maternal inflammation, and molecular alterations are critical to the development of mental illnesses, and we have identified SST and its receptor, SSTR2, as potential mediators of gestational inflammation-related risk for schizophrenia." (PMID 32029751, 2020). "The deficits in SST and SST+ neurons observed in subjects with schizophrenia and animal models of schizophrenia may be a downstream consequence of impaired BDNF signaling." (PMID 33192369, 2020). "In patients with schizophrenia and bipolar disorder, somatostatin-immunoreactive neurons are decreased in the lateral amygdala, which may affect responses to fear and anxiety." (PMID 32802040, 2020). "A subsequent study in schizophrenic subjects (post mortem tissue) found that decreased SST expression in the dorsolateral PFC in schizophrenia is confined to layers 2 through 6, and both the density of SST+ neurons and the expression of SST mRNA per neuron were reduced." (PMID 33192369, 2020). "Furthermore, lower somatostatin levels were measured in the cerebrospinal fluid and the brain areas of patients with major and bipolar depressive disorders, schizophrenia, Alzheimer’s, and Parkinson’s diseases." (PMID 30903571, 2019). "Taken together, evidence suggests that a deficit in intrinsic GABAergic signaling may contribute to the pathophysiology of schizophrenia; however, the relative contributions of PV and SST neurons throughout different brain regions is yet to be established." (PMID 31636253, 2019). "Somatostatin deficits in schizophrenia are demonstrated by a reduction of CSF somatostatin, decreased somatostatin gene expression in the dlPFC, and decreased number and density of somatostatin-expressing neurons in the hippocampus, caudal entorhinal cortex and parasubiculum." (PMID 24058344, 2013). "Identifying genes that are regulated by LHX6 may help inform molecular mechanisms of the alterations in PV and SST neurons in schizophrenia." (PMID 22937123, 2012). "Consistent to the current results, mRNA levels of SST in the PFC are decreased in schizophrenia patients in a study using in situ hybridization and another microarray study reported that both SST and NPY expression levels are decreased in the PFC of schizophrenia." (PMID 18992145, 2008). "Furthermore, reduced expression of SST is a hallmark of various neurodegenerative and neuropsychiatric disorders, such as AD, PD, HD, major depressive disorder (MDD), bipolar disorder, and schizophrenia (SCZ)." (PMID 36902271, 2023). "Subsequently, these changes to SST+ interneurons might also contribute to the gamma oscillation deficits seen in schizophrenia and our minimalistic model, consisting only of pyramidal cells and PV+ interneurons might not capture the full nature of SCZ-associated changes." (PMID 35854005, 2022). "SST mRNA is reduced in the dlPFC of patients with schizophrenia and may imply a clinical deficit." (PMID 34731619, 2021).
schizophrenia (continued). "We found that selectively decreasing PV or SST mRNA expression in the vHipp of Sprague–Dawley rats (male and female rats combined) is sufficient to produce baseline hippocampal hyperactivity consistent with that observed in rodent models and individuals with schizophrenia." (PMID 31636253, 2019). "Alterations of GABAergic interneurons, particularly parvalbumin (PV) and somatostatin (SST) subtypes, are frequently observed in schizophrenia." (PMID 39381500, 2024). "Ten patients with OCD exhibited significantly elevated serum autoantibodies to somatostatin and prodynorphin compared with 25 healthy controls and patients with advanced immunodeficiency virus (HIV), schizophrenia, Alzheimer’s disease, and multiple sclerosis." (PMID 37400462, 2023). "In the cortex, schizophrenia cases with a high inflammatory biotype have lower GAD1, SST, and PV mRNAs when compared to schizophrenia cases with the low inflammatory biotype." (PMID 34174930, 2021). "We present the first rodent MIA study of cortical and striatal deficits in SST and SSTR2 gene expression that concurs with cortical SST and SSTR2 mRNA deficits found in post-mortem schizophrenia studies." (PMID 32029751, 2020). "We present the first report of reduced SST mRNA in both cortex and striatum in the rat MIA model of schizophrenia." (PMID 32029751, 2020). "Here we have focused on somatostatin, a GABA marker, down-regulated in MDD, schizophrenia, bipolar disorder, and neurodegenerative diseases." (PMID 24058344, 2013). "pH accounted for significant amounts of variance in parvalbumin (12%), somatostatin (36%), DLG4 (13%) and PPP1R9B (11%) in the schizophrenia group." (PMID 22545112, 2012). "The link between differential tonic inhibition in SST and PV interneurons suggests that the GABAA receptor δ subunit may be a possible target for schizophrenia/epilepsy drugs." (PMID 37545878, 2023). "In an attempt to identify a potential molecular mechanism underlying the difference in mTL theta power and mPFC-mTL phase coupling between controls and subjects with schizophrenia, we turned to PET imaging of α5-GABAARs, found on hippocampal interneurons expressing somatostatin." (PMID 32236540, 2020). "In addition, an overlapping group of 33 schizophrenia and 29 control subjects underwent PET to measure the availability of GABAARs expressing the α5 subunit (concentrated on hippocampal somatostatin interneurons)." (PMID 32236540, 2020). "In order to put changes in TNFSF13 mRNA levels in the context of known schizophrenia neuropathology, we explored the relationship between levels of TNFSF13 mRNA and transcript levels of interneuron markers, somatostatin and parvalbumin, as well as spine markers, DLG4 and PPP1R9B." (PMID 22545112, 2012). "A microarray study reported that SST gene expression is increased in the PFC of bipolar disorder but not with schizophrenia patients." (PMID 18992145, 2008). "Several studies in schizophrenia patients found an altered expression of GABAA receptor subunits and GABA synthesis in the cerebral cortex, and electrophysiological dysfunction in parvalbumin and somatostatin GABAergic interneurons in the cortex and hippocampus." (PMID 34943962, 2021). "To test our hypotheses, we sought to determine in a human midbrain cohort (28/28 and 28/26 control/schizophrenia cases for mRNA and protein, respectively), whether GAD1 mRNA and GAD protein, as well as PV, SST and VGAT mRNA transcripts are lower in the midbrain in schizophrenia." (PMID 34174930, 2021). "There have been evidences suggesting that the somatostatin (SST) and neuropeptide-Y (NPY) expression in the amygdalar neurons plays a key role in the regulations of fear and stress responses as well as anxiety which manifest over the entire trajectory of schizophrenia." (PMID 32765318, 2020).
schizophrenia (continued). "Consistent with this hypothesis, strong positive correlations between BDNF protein levels and SST mRNA levels were observed in the PFC of human subjects (post mortem tissue) with schizophrenia, suggesting that BDNF may function to regulate SST expression in the PFC." (PMID 33192369, 2020). "Our novel finding of SST and SSTR2 mRNA reductions in striatum suggests that further examination of SST-related neurotransmission may be warranted in the striatum of people with schizophrenia." (PMID 32029751, 2020). "Notably, many of the genes that are DE only in subjects that died at night are genes consistently implicated in schizophrenia in other DE studies (e.g., BDNF, PVALB, SST) which have not taken time of death into consideration (e.g.,18–24)." (PMID 31399567, 2019). "Thus, we propose that an imbalance in inhibitory (SST‐IR) and excitatory (Ctip2‐IR) neurons in the IUGR fetal guinea pig brain could lead to excitatory/inhibitory dysfunction commonly seen in neurodevelopmental disorders such as autism and schizophrenia." (PMID 36373424, 2023). "Interestingly, a subset of schizophrenia subjects was identified by the presence of consistent deficits in LHX6, GAD67, PV and SST mRNAs, suggesting that LHX6 deficits may affect development and/or maintenance of GABAergic phenotype in PV and SST neurons in these subjects." (PMID 22937123, 2012). "In two different rodent models of schizophrenia, the MK-801 model in Long Evans rats and the BRINP1-KO model in mice, the number of SST+ immunoreactive neurons is decreased, although this does not necessarily represent a change in the SST peptide." (PMID 33192369, 2020).